CGAS (cyclic GMP-AMP synthase)
Diseases named in the same sentence as CGAS in open-access papers (continued):
Sharing a sentence is not in itself a finding about the gene and the disease.
tumor (continued). "Under the condition that the cGAS-STING pathway is activated within the BRCA TME, increased persistence of T helper/IL-17-producing CD8+ T -generated CAR-T cells is observed in the TME and enhanced tumor control." (PMID 39185402, 2024). "Surprisingly, we find that host STING-mediated vascular normalization and anti-tumor immune response depends on tumor cGAS, but not host cGAS." (PMID 38177099, 2024). "5-FU treatment significantly reduced tumour numbers and sizes in wild-type littermate control mice but not cGAS-KO mice." (PMID 39080411, 2024). "Chromosomal instability can impact tumour immune infiltration and inflammation via the activation of the cyclic guanosine monophosphate–adenosine monophosphate (GMP–AMP) synthase–stimulator of interferon genes (cGAS–STING) pathway, leading to suppression of anti-tumour immunity." (PMID 39337605, 2024). "Depletion of cGAS, STING, IRF3, or IFNα/β receptor 1 (IFNAR1) abolishes this increase, indicating that 5-FU/oxaliplatin mediated upregulation of PD-L1 expression is dependent on tumor cell intrinsic cGAS/STING signaling." (PMID 39469633, 2024). "Consequently, the impact of cGAS-STING on cancer outcomes depends on various factors, including tumor type, the host’s immune profile, specific cell types activated, therapeutic approach employed, and the degree of cGAS-STING activation." (PMID 38817608, 2024). "Although the cGAS/STING pathway plays an essential role in inducing an anti-tumour inflammatory response, the current approach does not favour relying on cGAS/STING as a standalone immunotherapeutic target." (PMID 39403376, 2024). "Intriguingly, some scholars found that cGAS could exert the function of maintaining CIN, which potentiated tumor evolution." (PMID 38510490, 2024). "As a result of activating the cGAS/STING pathway, LEV@DOX@REV could prevent tumor relapse and metastasis." (PMID 38868091, 2024). "Additionally, a positive correlation was found between tumor TET2, STAT5A, cGAS expression and intratumoral CD8+ T cell infiltration." (PMID 38177099, 2024). "Activation of cGAS in response to cytosolic DNA leads to downstream effects via the canonical STING pathway and non-canonical signaling molecules critical in both exacerbation of inflammation in IBD and enhancement of the tumor microenvironment in cancers." (PMID 39050748, 2024). "The cyclic GMP-AMP synthase-stimulator of interferon genes (cGAS-STING) pathway has gained significant attention due to its ability to activate the production of type I interferon, thereby enhancing anti-tumor immune responses." (PMID 39995821, 2024). "These reasons may explain why tumor cGAS is essential for host STING activation and thereby host STING-mediated vascular normalization and anti-tumor immune response, whereas cGAS of host cells is dispensable." (PMID 38177099, 2024). "To examine the role of HSP60 oligomerization in cGAS/STING signaling and anti-tumor immunity, we aimed to determine whether the HSP60 mutant with defective oligomerization exhibits phenotypes similar to those observed in the methylation-defective mutant." (PMID 39256398, 2024). "cGAS-STING pathway is vital for anti-tumor immunity, but its role in tumor vasculature is unclear." (PMID 38177099, 2024). "Research has also indicated that upon recognition of CIN, cGAS activates non-canonical NF-κB, contributing to a program that enhances tumor metastasis." (PMID 38817608, 2024). "Moreover, the immunity can be activated by FeO1‐xOH through cGAS‒STING pathway, and the tumor cell proliferation will be suppressed by allicin, diminishing the possibility of tumor recurrence." (PMID 39031565, 2024). "Therapeutically, this suggests the potential cross-applicability of cGAS inhibitors, which could dampen hyperactive immune responses in IBD or modify the tumor microenvironment in GI cancers, presenting a dual benefit." (PMID 39050748, 2024).
tumor (continued). "To better characterise the level of MOMP in tumour tissues, based on previous research methods, we integrated the effector pathways directly activated by MOMP (apoptosis, necroptosis, cGAS/STING, NF‐kB and inflammasome pathways) to calculate MOMP activity in tumour tissues." (PMID 38899748, 2024). "In this process, the expression of cGAS in tumor cells rather than in non-tumor cells is necessary for the NK cell-mediated anti-tumor effect." (PMID 38523155, 2024). "To identify whether the cGAS‐STING pathway may contribute to Mn‐N/C‐induced type I IFNs production, we pre‐treated MC38 tumor cells with a STING inhibitor (H151) and observed a significant suppression type I IFNs induction upon Mn‐N/C plus H2O2 treatment." (PMID 38308189, 2024). "However, as the function of the cGAS-STING pathway remains to be elucidated, there is increasing evidence that it mediates anti-tumor immunity and plays a key role in promoting malignant tumor progression." (PMID 39464890, 2024). "In addition, we discovered that Mn2+ has the potential to activate the cGAS–STING signaling pathway, thereby augmenting the cross-presentation of DCs through IFN-β production and subsequently activating tumor-specific CD8+ T cells." (PMID 38715912, 2024). "For instance, in cases where DSBs occur within cancer cells, cGAS relocates to the nucleus, thereby impeding the formation of PARP1–TIMELESS complexes, which inhibit homologous recombination (HR) repair and sustain CIN, thereby facilitating tumor evolution." (PMID 38817608, 2024). "This indicates that ARID1A loss can impact immune response to tumor cells via other mechanisms, and it is not restricted only to DSB repair deficiency and activation of cGAS/STING pathway." (PMID 38587186, 2024). "Secondly, our study focused on the effect of the cGAS‐STING pathway on tumor cells; however, its influence on the tumor microenvironment in PTCL remains unclear." (PMID 38145335, 2024). "The cGAS-STING pathway plays a crucial role in innate immune recognition of immunogenic tumors, facilitating APC maturation, cytokine secretion, and CD8+ T cell development targeting tumor-specific antigens." (PMID 39061208, 2024). "Additionally, the POLE P286R mutant also increases cGAS level, promotes TBK1 phosphorylation, and stimulates inflammatory gene expression and anti-tumor immune response." (PMID 38238314, 2024). "Furthermore, T-DXd activated dendritic cells via the cancer cell-intrinsic cGAS-STING-IFN axis and enhanced PBMC-mediated tumor cell killing by activating CD8+ T cells." (PMID 39449023, 2024). "This process is mediated by RAB22A-mediated non-canonical autophagy and can promote anti-tumor immunity, adding a new dimension to our understanding of cGAS-STING signaling in the TME." (PMID 38523155, 2024). "Moreover, tumor-derived cyclic GMP-AMP (cGAMP), a critical activator of the cGAS-STING pathway, can be derived from cancer cells and transferred into neighboring cells, directly activating STING in the TME." (PMID 39450170, 2024). "In addition, the expression of cGAS and STING proteins varies across different types of tumor cells." (PMID 39295867, 2024). "The cGAS is the direct cytosolic DNA sensor and innate immune response initiator, which binds to cytosolic DNA and activates STING as a downstream adaptor through the generation of the second messenger cyclic GMP-AMP (cGAMP) on tumor cells and DCs." (PMID 38791963, 2024). "Furthermore, RT with the blockade of CD73 led to the activation of cellular cGAS-STING and IFN-I pathways, which played a critical role in initiating tumor-specific immune responses mediated by CD8 + T cells." (PMID 39285178, 2024).
tumor (continued). "Differential cGAS-STING pathway activity between normal and tumor cells could result in the FLASH-RT effect, potentially impeding tumor growth while protecting normal tissue from severe injuries, such as pulmonary fibrosis." (PMID 39684218, 2024). "The cGAS‐STING pathway is oncogenic in PTCL, whereas targeting cGAS suppresses tumor growth, and CLK1 may be a sensitivity indicator for cGAS inhibitors." (PMID 38145335, 2024). "In summary, our work reveals a new mechanism by which tumor cells can secrete exosomes that carry ENPP1 to effectively hydrolyze 2′3′‐cGAMP and LL‐37‐2′3′‐cGAMP in the tumor microenvironment and, therefore, inhibit the cGAS‐STING pathway in immune cells." (PMID 38498770, 2024). "Moreover, as a potent activator of the cGAS-STING pathway, manganese ions can significantly enhance the host's anti-tumor immune function, effectively reducing the cost of tumor immune therapy." (PMID 38512518, 2024). "This review focuses on the molecular mechanism of the cGAS-STING signaling pathway, analyzing its relationship to tumor immunity, and discussing how the innate immune pathway cGAS-STING transforms “cold” tumors into “hot” tumors, thereby further enhancing the therapeutic effect of ICIs." (PMID 38817608, 2024). "Herein, we provide evidence demonstrating that INDO-mediated COX2 inhibition augments MUS81-mediated cytoplasmic tumor DNA accumulation and cGAS/STING/type I IFN, which restored tumor immune surveillance via potent antitumor innate and adaptive immune responses in irradiated 4T1 TNBC tumors." (PMID 38912586, 2024). "Both in vitro and in vivo results demonstrated that MAPN can precisely activate the cGAS‐STING pathway and block the PD‐1/PD‐L1 pathway, and thus initiating robust and durable anti‐tumor immune responses to inhibit the growth, recurrence, and metastasis of malignant tumors." (PMID 38233164, 2024). "Tumor-specific adaptive immune responses, including the activation of cytotoxic T cells (CD8+ T cells), rely on type I interferon signaling from antigen-presenting cells, with the cGAS-STING pathway being a critical mediator of type I interferon activation." (PMID 39763653, 2024). "By triggering “eat me” signals in tumor cells, DOX might help DCs phagocytize apoptotic tumor cells, while REV can activate the cGAS/STING pathway, increase CTL infiltration, and enhance the effect of chemotherapy and immunotherapy." (PMID 38868091, 2024). "However, the promoter regions of cGAS and STING1 in tumour cells are usually highly methylated and silenced or have a loss of function mutation." (PMID 37488750, 2023). "dsDNA from micronuclei as well as DNA damage induction will be recognized by the cytoplasmic DNA sensor cGAS, thereby activating the cGAS-STING signaling pathway, shaping innate immunity in a type I IFN-dependent manner, promoting adaptive immune responses, and thus effectively anti-tumor." (PMID 37667279, 2023). "Indeed, it is becoming more and more evident that the cGAS-STING pathway exerts a controversial role in cancer, supporting diverse and sometimes opposing functions, favoring tumor progression in some contexts." (PMID 38203626, 2023). "However, cGAS and AIM2 have been found to respond to pathogen-derived DNA, self-DNA, and tumor-derived DNA." (PMID 37046775, 2023). "Furthermore, the cytosolic DNA in DCs triggers cGAS/STING signaling-dependent type 1 IFN release, further supporting DC maturation and tumor antigen presentation to CD4+ and CD8+ T cells." (PMID 37380989, 2023). "Moreover, the over‐expressed cGAS and cytosolic sensor NLRP3 colocalized with the tumor‐derived DNA and exogenous oxLDL in DCs, respectively." (PMID 37786300, 2023). "Second, the presence of extensive DNA damage in tumor cells due to DNA-damaging agents or endogenous deletion of DDR, leads to activation of the cGAS-STING signaling pathway, which may trigger type 1 interferon-mediated T cell activation." (PMID 36776314, 2023).
tumor (continued). "As an additional immune evasion strategy, tumour cells can also re-wire cGAS-mediated STING signalling towards increased non-canonical NF-κB activation in cancer cells through the NF-κB subunits p52 and RelB." (PMID 37534795, 2023). "ER−breast cancers (BCs) and triple -negative breast cancers (TNBCs) also offer little to no IRF8 expression, indicating that impaired cGAS/STING signaling supports tumor growth and metastasis due to decreased antitumor CD8+T cell infiltration." (PMID 37380989, 2023). "Therefore, it becomes critical to understand and discuss the role of cGAS/STING signaling in the MIC compartment of the TIME and its impact on the tumor microenvironment (TME) or TIME." (PMID 37380989, 2023). "More recently, it has become evident that PARP1 inhibition can directly activate the cGAS/STING pathway independent of the BRCA status of the tumor." (PMID 37420037, 2023). "However, persistent activation of cGAS-STING led to a reduction in type I IFNs production and an increase in atypical NF-κB signaling in tumor cells with chromosomal instability." (PMID 37920470, 2023). "The expression of cGAS-STING in tumor cells did not have a significant impact on patient survival with pMMR CRC within ten years after curative resection." (PMID 37345163, 2023). "The enhanced TBK1 and IRF3 activation should increase the sensitivity of TYST cells to CD8+ T‐cell‐mediated killing in the co‐culture system while cGAS silencing usually attenuated the cGAS‐STING signaling to reduce IFN‐β production and CD8+ T‐cell infiltration, promoting tumor growth." (PMID 37986544, 2023). "Tumor irradiation with one to three fractions of 8 Gy results in double-stranded DNA fragments in the cytoplasm of cancer cells and induction of the cGAS/STING (cyclic GMP-AMP synthase and stimulator of interferon genes) pathway." (PMID 37894449, 2023). "By boosting the cGAS/STING pathway, PARPis sustain inflammation and the secretion of IFN-I and several other cytokines and chemokines, resulting in recruitment of immune cells, including tumor antigen-specific CD8 T cells." (PMID 36831435, 2023). "Our models might therefore not recapitulate the antitumor effect of SE12C3 dependent on DCs—in particular, that mediated by the cGAS-STING pathway, which is activated by anti-CD47 in a syngeneic mouse tumor model." (PMID 38162643, 2023). "RT induces DNA-sensing pathways, such as the cGAS-STING pathway, in host or tumor cells to upregulate the production of type I interferon, which in turn activates tumor-infiltrating dendritic cells (DC) to augment their activity to cross-prime tumor-specific CD8+ T cells." (PMID 38069014, 2023). "We then asked whether the inverse relationship between cGAS activity and STING protein levels can be recapitulated in human tumour samples." (PMID 37612508, 2023). "Recent studies report that activation of the cGAS-STING pathway can be used to enhance antitumor immunotherapy, in part due to the induction of type I interferons which enhance the recognition of tumor cells and the killing efficiency of T cells." (PMID 37816954, 2023). "This stimulation is induced by the cGAS/STING signaling-dependent proliferation of type 1 IFNs and NF-κB-responsive genes, which promotes a chronic proinflammatory environment that supports tumor growth." (PMID 37508372, 2023). "In recent decades, cGAS-STING pathway, which can congenitally recognize exogenous and endogenous DNA for activation, has been widely reported to play critical roles in the innate immunity against some important diseases, such as infections and tumor." (PMID 37153576, 2023). "Mouse tumor-bearing models lacking cGAS or STING were more prone to tumor growth, and in models, the deficiency of cGAS and STING impaired the response of mouse models to immune checkpoint inhibitor therapy." (PMID 37920470, 2023).
tumor (continued). "Recently, studies have also demonstrated that mtDNA released into the cytosol of irradiated tumor cells failed to activate the cGAS-MITA/STING pathway due to caspase 3/9-mediated suppression of this signaling pathway." (PMID 37932533, 2023). "The cGAS-STING pathway explains the immunomodulatory function of classical cancer therapy,The cGAS-STING pathway enhances the anti-tumor immune response by detecting the formation of micronucleus induced by DNA damage and chromatin fragments present in the cytoplasm." (PMID 37920470, 2023). "Our defined PRMT1-cGAS signaling axis might partially explain the synergistic effect of inhibition of PRMT1 and PRMT540, in which both the parallel cGAS and IFI16 signaling might be activated to maximal downstream cascade to trigger anti-tumor immunity." (PMID 37193698, 2023). "Moreover, IHC staining showed increased protein levels of TET2, cGAS, STING and TBK1 in TET2-overexpressing tumours, in which the protein levels of STING and TBK1 were clearly decreased by RU.521 treatment." (PMID 37667220, 2023). "Simultaneously, MnO2 catalyzed hydrogen peroxide (H2O2) to produce oxygen with tumor hypoxia alleviation and radiotherapy efficacy enhancement, and the released Mn2+ activated the cyclic GMP-AMP (cGAS)-stimulator of interferon genes (STING) pathway and triggered tumor-specific immunity." (PMID 37766117, 2023). "We supposed that the MTHMS + L induced cGAS-STING pathway activation related to IFN-β secretion may contribute to DC maturation, which induced the subsequent T cell activation in tumor-draining lymph nodes (TDLNs)." (PMID 37221157, 2023). "This leads to cGAS-STING pathway activation and type I interferon (IFNα/β) production, which may potentiate CD8+ T cell-mediated tumor destruction." (PMID 37568764, 2023). "Also, we identify an unappreciated role for the cGAS-STING pathway in mediating the immunoregulatory activity of plant-derived nanovesicles, opening an avenue for developing new anti-tumor strategies, alone or combination with αPD-L1." (PMID 36879291, 2023). "Recent reports indicate that cGAS/STING pathway activation promotes tumor metastasis through the activation of the noncanonical NF-kb pathway." (PMID 37354378, 2023). "Increasingly recognised as a potent stimulator of anti-tumour immunity, activation of cyclic GMP–AMP synthase (cGAS)-stimulator of interferon genes (STING) results in a cascade sequence within the innate immune system, driving interferon production and heightening T-cell responses." (PMID 36831687, 2023). "Further exploration of ATM inhibitors confirmed that ATM inhibition may upregulate Gal-9 expression through the cGAS-STING-IFN-β signaling pathway, an important mechanism mediating tumor immune escape." (PMID 37305685, 2023). "The cGAS-STING pathway mediates induction of CXCL9/10 in DCs; therefore, STING agonists are potential as therapeutic agents for activating DCs and recruiting T lymphocytes in tumor treatment." (PMID 36688994, 2023). "The presence of cGAS/STING signaling in both tumor cells and immune-competent mice is essential for anti-tumor immunity, and depletion of cGAS and/or STING in either tumor cells or immune-competent mice robustly dampen the tumor immunogenicity and efficiency of immunotherapy." (PMID 37193698, 2023). "By stimulating cGAS-STING signaling, A3A elicits the infiltration of anti-tumor CD8+ T cells." (PMID 37215984, 2023). "Activation of the interferon gene cyclic GMP-AMP synthase-stimulator of interferon genes (cGAS-STING) pathway produces a variety of pro-inflammatory chemokines and cytokines, such as IFN, to trigger the innate immune response of the body against tumor." (PMID 37457707, 2023). "We found that tumor cell-intrinsic expression of cGAS, but not STING, was significantly reduced in pMMR/MSS CRC from patients who experienced recurrence within five years after curative resection." (PMID 37345163, 2023).